PAK4 (p21 (RAC1) activated kinase 4)
Diseases named in the same sentence as PAK4 in open-access papers (continued):
Sharing a sentence is not in itself a finding about the gene and the disease.
Cachexia (1 paper, 2025). Severe weight loss, wasting of muscle, loss of appetite, and general debility related to a chronic disease. "Selective elevation of PAK4 protein, with no changes in other PAK members, and AMPKα2 phosphorylation at S491 were consistently observed in various muscle atrophy models, including those induced by cancer cachexia, hindlimb suspension, and aging." (PMID 41328324, 2025).
cerebral cavernous malformation (1 paper, 2016). A disorder characterized by malformations in the structure of the capillaries in the brain. "Src activity has been reported to inhibit the Rho/Rock pathway, a pathway also inhibited by Pak2/Pak4, Rasip1/Arhgap29, and the cerebral cavernous malformation (CCM) proteins, CCM1 and CCM2." (PMID 26812085, 2016).
cervical tumor (1 paper, 2021). "There was a significant PAK4 upregulation in cervical tumor tissues compared with normal margins which were correlated with FIGO stage, grade, and lymph node involvement." (PMID 37303943, 2021). "PAK4 also promotes the cisplatin resistance in cervical tumor cells through PI3K/AKT pathway." (PMID 37303943, 2021).
colon adenocarcinoma (1 paper, 2022). "In colon cancer (colon adenocarcinoma, COAD) cells, PAK4 boosts glucose intake and NADPH production, thereby mediating COAD cell proliferation." (PMID 35800076, 2022).
cyst (1 paper, 2021). A sac-like closed membranous structure that may be empty or contain fluid or amorphous material. "When MDCK cells were cultured in matrigel, they undergo cyst formation and the segregation of PAK4 away from cadherin junctions was most obvious with PAK4 exclusively apical." (PMID 34493720, 2021).
endometrioid ovarian carcinoma (1 paper, 2024). "The P value between normal ovarian tissue and serous ovarian carcinoma, mucinous ovarian carcinoma and endometrioid ovarian carcinoma in Pak4 expression was 0.0044, 0.01755 and 0.0233, respectively." (PMID 38807162, 2024). "In this work, we demonstrated that Pak4 was highly expressed in serous, mucinous and endometrioid ovarian cancer." (PMID 38807162, 2024). "Positive rate of Pak4 in endometrioid ovarian cancer was 71.4% (5/7)." (PMID 38807162, 2024).
endometriosis (1 paper, 2026). The growth of functional endometrial tissue in anatomic sites outside the uterine body. "Together, our findings establish a senescence-driven PAK4/AKT signaling circuit that fosters an aggressive, immunomodulatory endometriosis subtype and identify stigmasterol as a promising senescence-targeted therapeutic agent." (PMID 41891132, 2026).
epithelial ovarian tumors (1 paper, 2018). "This study confirmed that miR-24-1-5p could promote epithelial ovarian tumors by negatively regulating PAK4 expression." (PMID 29440672, 2018). "This implies that LINC01088 might inhibit the development of epithelial ovarian tumors through its interaction with miR-24-1-5p and the downstream effector protein PAK4." (PMID 29440672, 2018).
gallbladder carcinoma (1 paper, 2023). "Although it has been reported that PAK4 is overexpressed in gallbladder cancer during the evaluation of gene expression profiles of gallbladder cancers, studies on PAK4 and PHF8 in gallbladder cancer have been limited." (PMID 36980457, 2023). "Therefore, this study evaluated the expression patterns and the association of PAK4 and PHF8 in human gallbladder carcinomas (GBCs) and assessed the prognostic significance of their expression patterns." (PMID 36980457, 2023). "Multivariate analysis showed that nuclear PAK4 expression and nuclear PHF8 expression were independent predictors of overall survival and relapse-free survival in gallbladder carcinomas." (PMID 36980457, 2023). "Furthermore, coexpression of nuclear PAK4 and nuclear PHF8 predicted shorter overall survival (p < 0.001) and relapse-free survival (p < 0.001) of gallbladder carcinoma in multivariate analysis." (PMID 36980457, 2023). "However, despite extensive studies in human cancers, there are limited reports on the roles of PAK4 and PHF8 in gallbladder cancers." (PMID 36980457, 2023). "Moreover, considering that PAK4 shows its kinase activity upon interaction with CDC42 and CDC42 signaling is regulated by PHF8, there might be potential relationships between the roles of PAK4 and PHF8 in the progression of gallbladder cancers." (PMID 36980457, 2023).
Insulin resistance (1 paper, 2025). Increased resistance towards insulin, that is, diminished effectiveness of insulin in reducing blood glucose levels. "We recently identified that AMP‐activated protein kinase (AMPK) α2 phosphorylation at S491 is mediated by p21‐activated kinase 4 (PAK4), leading to muscular and systemic insulin resistance." (PMID 41328324, 2025).
invasive carcinoma (1 paper, 2016). A carcinoma that is not confined to the epithelium, and has spread to the surrounding stroma. "The positive rate of PAK4 expression in noninvasive carcinoma, early invasive carcinoma, and advanced invasive carcinoma increased gradually, and the differences were all statistically significant." (PMID 27297086, 2016). "Besides, the positive rate of PAK4 expression in noninvasive carcinoma, early invasive carcinoma, and advanced invasive carcinoma also increased gradually." (PMID 27297086, 2016).
liver cirrhosis (1 paper, 2023). "The factors significantly associated with PAK4 expression at these cut-off points were liver cirrhosis (P = 0.034) and tumor stage (P = 0.023)." (PMID 37591884, 2023).
liver steatosis (1 paper, 2023). "Our results collectively suggest that inhibiting PAK4 might be a therapeutic target for preventing hepatic steatosis." (PMID 37591884, 2023). "Furthermore, serum and hepatic triglyceride (TG) levels, gross liver morphology, and histochemical analysis (H&E and Oil Red O staining) demonstrated that liver steatosis induced by fasting or KD-feeding was exacerbated by PAK4 overexpression, but not PAKS474A." (PMID 37591884, 2023).
lymphoma (1 paper, 2021). A malignant (clonal) proliferation of B- lymphocytes or T- lymphocytes which involves the lymph nodes, bone marrow and/or extranodal sites. "Here, we show that p21-activated kinase 4 (PAK4) and nicotinamide phosphoribosyl transferase (NAMPT) is critical for lymphoma subsistence." (PMID 35008323, 2021). "Given the role of NAMPT and PAK4 in lymphoma biology, dual inhibition of NAMPT-PAK4 appears to be a promising therapeutic strategy." (PMID 35008323, 2021).
metastatic disease (1 paper, 2021). "Additionally, given the importance of PAK4 in metastatic disease, studies should be conducted to understand if the role of PAK4 differs in an ES cell of a primary tumor vs. an ES cell at a metastatic site." (PMID 36594908, 2021).
muscle atrophy (1 paper, 2025). The loss of muscle tissue due to inactivity or disease. "To determine whether the PAK4 protein level is altered under sarcopenic conditions, we examined it in different mouse models of muscle atrophy." (PMID 41328324, 2025).
nasal polyp (1 paper, 2025). "NEAT1 promotes EMT in nasal polyp epithelial cells by modulating the miR-199-3p/PAK4 axis, highlighting its potential as a diagnostic biomarker and therapeutic target in CRSwNP." (PMID 40661947, 2025). "In vivo validation was performed using a mouse nasal polyp model, and molecular interactions among NEAT1, miR-199-3p, and PAK4 were confirmed via dual-luciferase reporter assays." (PMID 40661947, 2025). "In our preliminary transcriptomic analysis of nasal polyp epithelial cells, we identified PAK4 (p21-activated kinase 4) as a potential downstream effector of NEAT1." (PMID 40661947, 2025). "Additionally, immunohistochemical analysis of clinical samples revealed that PAK4 expression was higher in nasal polyp tissues compared to normal nasal mucosa." (PMID 40661947, 2025).
ovarian tumors (1 paper, 2013). "An association of the proliferative status of ovarian tumors with survival has been reported before, using p21-activted kinase 4 (Pak4) or cell cycle-related kinase (CCRK) as markers." (PMID 24044611, 2013).
papilloma (1 paper, 2015). A benign epithelial neoplasm that projects above the surrounding epithelial surface and consists of villous or arborescent outgrowths of fibrovascular stroma. "Moreover authors observed that when coupling phosphoproteomics and prediction of kinase activity, in this research study, PAK4-PKC/SRC network was highly deregulated in SCC although it was not in papilloma." (PMID 26055493, 2015).
respiratory failure (1 paper, 2017). The significant impairment of gas exchange within the lungs resulting in hypoxia, hypercarbia, or both, to the extent that organ tissue perfusion is severely compromised. "Increased pulmonary microvascular permeability contributes to respiratory failure in ALI; PAK4-associated pulmonary vascular cytoskeletal rearrangement is also involved in increased vascular permeability, alveolar edema, and LPS-induced ALI." (PMID 29445744, 2017).
Salmonella Infections (1 paper, 2023). Infections with bacteria of the genus SALMONELLA. "In the AOM/DSS mouse model, lower CDC42 K153 acetylation caused by Salmonella infection is associated with higher PAK1 phosphorylation but lower PAK4 phosphorylation." (PMID 36812247, 2023). "We find that CDC42 K153 can be deacetylated by the NAD+-dependent deacetylase SIRT2 after Salmonella infection, which causes an impaired binding of its downstream effector PAK4." (PMID 36812247, 2023). "The results confirmed that the phosphorylation levels of JNK and p38 were reduced after PAK4 knock down, and the phosphorylation level of p38 was still lower in PAK4 knockdown cells even after Salmonella infection." (PMID 36812247, 2023). "The results of western blot assay showed that PAK4 phosphorylation level appeared to be lower in the AOM/DSS-treated mice group with Salmonella infection than in the uninfected mice group, whereas PAK1 phosphorylation level showed the opposite trend." (PMID 36812247, 2023). "In this study, although the acetylation of CDC42 K153 is recognized as a key step regulating the interaction between CDC42 and PAK4, other Salmonella infection-induced PTMs of CDC42 may also change the affinity between these two proteins." (PMID 36812247, 2023). "In summary, we found that Salmonella infection decreased the acetylation level of CDC42 K153 through SIRT2, and the low acetylation level of CDC42 K153 could block the interaction between CDC42 and PAK4." (PMID 36812247, 2023). "In HEK293T cells with stable knockdown of SIRT2, Salmonella infection failed to reduce K153 acetylation and the binding of CDC42 to PAK4 was restored." (PMID 36812247, 2023).
sarcoma (1 paper, 2023). A usually aggressive malignant neoplasm of the soft tissue or bone. "KPT-9274 is a dual NAMPT/p21-activated kinase 4 (PAK4)/inhibitor that decreases the NAD+/NADH ratio in cancer cells, inhibiting tumor growth in sarcoma mice models and RCC." (PMID 37046703, 2023).
sarcopenia (1 paper, 2025). Progressive decline in muscle mass due to aging which results in decreased functional capacity of muscles. "In contrast, AMPKα2‐S491 phosphorylation was elevated in individuals with muscle loss and correlated with increased PAK4 levels or the severity of sarcopenia." (PMID 41328324, 2025). "This study reveals that PAK4 protein is overexpressed and activated in various mouse and human models of sarcopenia." (PMID 41328324, 2025). "This study examined how muscle PAK4 deletion affects atrophy in male mice and its link to human sarcopenia." (PMID 41328324, 2025). "Compared with non‐sarcopenia controls, sarcopenic muscle tissues exhibited elevated PAK4 protein levels and increased phosphorylation of its downstream target, AMPKα2‐S491, along with upregulation of MuRF1 and Atrogin‐1." (PMID 41328324, 2025). "In humans, sarcopenic muscle exhibited higher levels of PAK4 protein and AMPKα2‐S491 phosphorylation compared with non‐sarcopenia controls, with an inverse correlation to sarcopenic index and grip strength." (PMID 41328324, 2025). "Together, these approaches aim to establish PAK4 not only as a molecular link between metabolism and muscle homeostasis but also as a promising therapeutic target for the prevention of sarcopenia and related muscle‐wasting disorders." (PMID 41328324, 2025). "Mechanistically, extending our previous findings, we show that PAK4 inhibits AMPKα activity through inhibitory phosphorylation at S491 of AMPKα2 in sarcopenia models." (PMID 41328324, 2025). "Our findings suggest that targeting PAK4 with PROTAC could be a viable therapeutic strategy for sarcopenia, making this the first study to demonstrate PROTAC as a potential treatment for the condition." (PMID 41328324, 2025). "Collectively, these results suggest that AMPKα activity is reduced in sarcopenia and that targeting PAK4 may serve as a potential strategy to restore AMPKα activity and mitochondrial function." (PMID 41328324, 2025). "Finally, to explore the potential role of PAK4 in human sarcopenia, we analyzed muscle samples from non‐sarcopenic individuals and sarcopenic patients across various age groups." (PMID 41328324, 2025). "Furthermore, we evaluated the efficacy of the PAK4‐targeted proteolysis‐targeting chimera (PROTAC) SJ‐05, which induces selective protein degradation, and examined PAK4 expression as well as its regulation of AMPK phosphorylation in human muscle tissues with sarcopenia." (PMID 41328324, 2025). "Therefore, PAK4 inhibitors could serve as a two‐in‐one strategy by enhancing anabolic signaling while reducing catabolic signaling in sarcopenia." (PMID 41328324, 2025).
cancer (141 papers, 2007 to 2026). A tumor composed of atypical neoplastic, often pleomorphic cells that invade other tissues. "PAK4 is highly associated with human cancers and promotes the proliferation and metastasis of various cancers, including ovarian, pancreatic, lung, and colorectal cancers, through its involvement in cytoskeletal remodeling and neurodevelopment." (PMID 39852144, 2025). "In multiple cancers, including head and neck cancer, PAK4 is commonly expressed and linked to disease aggressiveness, often correlating with a poor prognosis." (PMID 38890401, 2024). "A higher expression of PAK4 is associated with poor prognoses for patients with cancer in the ovaries, lungs, prostate, and liver." (PMID 39273017, 2024). "The expression level of PAK4 is often elevated in various types of cancers at DNA, RNA, or protein level, and is proposed as a diagnostic biomarker for cancer." (PMID 38424218, 2024). "Previous studies implicated PAK4 in cancer-related energy signaling pathways, such as mediating oncogenic transformation." (PMID 37532687, 2023). "PAK4 overexpression or activation in human tissues is often associated with cancer and oncogenic transformation." (PMID 35328758, 2022). "In human tumors, the overexpression and overactivation of PAKs kinases, especially PAK1 and PAK4, are usually associated with cancer, because both kinases are found to be elevated at DNA, RNA, or protein levels in many types of cancer." (PMID 36064705, 2022). "Overexpression or activation of the target protein PAK4 is often associated with cancer and oncogenic transformation." (PMID 35328758, 2022). "In many cancers, PAK4 is shown to be overexpressed or mutated, and its inhibition by pharmacological means is suggested to target cancer metastasis." (PMID 35593474, 2022). "It controls several cancer-associated genes, such as mammalian target of rapamycin (mTOR), hepatocyte growth factor receptor c-Met, the kinase p21-activated kinase 4 (PAK4), and the Notch regulator Yes-associated protein 1 (YAP1)." (PMID 31805631, 2019). "PAK1 and PAK4 levels are highly elevated in many cancers, and the other members of the PAK family are also linked to cancer." (PMID 31658701, 2019). "Transfection of pre-miR-199a-3p was associated with a significant decrease in PAK4 mRNA levels in all three cancer cell lines." (PMID 29983868, 2018). "While cancer cells are generally less susceptible to cell death, PAK4 knockdown dramatically induces apoptosis in these cells." (PMID 28198380, 2017). "Mounting evidence suggest that PAK4 expression is tightly correlated with cancer progression, which makes PAK4 a potentially promising diagnostic and therapeutic target for cancer therapy." (PMID 28178642, 2017). "Although, the involvement of PAK4 in cancer development has been well established, few studies have implicated the role of PAK4 in inflammation." (PMID 28680855, 2017). "In another study of 93 invasive breast carcinoma patients, high PAK4 levels were associated with advanced stage cancer, large tumor size, lymph node metastasis, and poor survival." (PMID 28198380, 2017). "The serine/threonine kinase PAK4 is a Cdc42 effector whose role is not well understood; overexpression of PAK4 has been associated with some cancers, and there are reports that correlate kinase level with increased cell migration in vitro." (PMID 26068882, 2015). "PAK4 activation/upregulation has been recognized to be associated with the malignance in various types of human cancers, such as cancers in ovarium, gaster, hypar." (PMID 26411419, 2015). "Especially for PAK4, it is strongly implicated in oncogenic transformation and its activity is required for Ras-driven anchorage-independent growth in various cancer cell lines." (PMID 27919028, 2014). "Pak4 has an important role in embryonic development, but in adult tissues Pak4 overexpression is often associated with cancer." (PMID 23326684, 2012).